ATR (ATR checkpoint kinase)
Diseases named in the same sentence as ATR in open-access papers (continued):
Sharing a sentence is not in itself a finding about the gene and the disease.
tumor (continued). "This sparked interest in therapeutically using ATM and ATR inhibitors as radio- or chemo-sensitizers, or as a monotherapy in tumours addicted to particular DNA repair pathways." (PMID 26610585, 2015). "The purpose of this study is to investigate the effects of the ATR inhibitor VE-821 in human tumor and normal cells irradiated with high LET carbon ions." (PMID 26286029, 2015). "When ATR activity was inhibited, high LET radiation caused more multiple micronuclei in the BN tumor cells." (PMID 26286029, 2015). "Free drug tumor levels of VX-970 were maintained for 48 hours after administration at concentrations well over that required to block ATR activity in cells." (PMID 25010037, 2014). "The improvement in survival was associated with a marked in vivo depletion in ATR, CHK1 and RAD52, but induction of γ-H2AX, cleaved Caspase 3 and BIM in the engrafted tumor cells following 1 week of treatment with the combination." (PMID 25026298, 2014). "This study describes the impact of inhibiting ATR by VX-970 on cell and tumor responses to DNA damaging drugs." (PMID 25010037, 2014). "Previous reports have shown that senescence can be induced by DNA damage in tumor cells through an ATM/ATR dependent mechanism." (PMID 23272087, 2012). "Caffeine as well as more specific inhibitors of ATM (KU55933) or ATM and ATR (CGK733) have recently been shown to induce cell death in drug-induced senescent tumor cells." (PMID 19903334, 2009). "Depletion of ATR or Chk1 leads to a consistent robust apoptotic response to replication inhibitors in both tumour and immortalized fibroblast cell lines." (PMID 19119425, 2009). "ATM and ATR/Chk1 signalling pathways were manipulated using siRNA-mediated depletions or specific inhibitors in two tumour cell lines or fibroblasts derived from patients with inherited mutations." (PMID 19119425, 2009). "In fact, it has been suggested that ATR acts as a haploinsufficient tumour suppressor under certain circumstances." (PMID 19440510, 2008). "Inhibition of ATR/Chk1 can sensitize tumor cells to A3 enzyme-dependent death." (PMID 41501001, 2026). "Mechanistic studies validated its ATR inhibition and DNA damage induction in treated tumours." (PMID 40256842, 2025). "In normal cells, ATR functions as tumor suppressor to maintain genomic integrity." (PMID 40940791, 2025). "While no formal proof, these data imply that there may be increased DNA damage response activity in tumor cells, which may be repressed by ATR inhibition." (PMID 39838187, 2025). "Western blot showed RGC32 knockdown could suppress ATM/ATR/CHK1 pathway and increase the tumor mutational burden (TMB)." (PMID 40740769, 2025). "Besides PARP-BRCA1/2 pairs, DDR sensor kinases ATM, ATR and DNA-PK recently gained attention as synthetic lethal partners in different tumour types, as demonstrated by the increasing number of their inhibitors in clinical trials." (PMID 40091075, 2025). "We demonstrated that the combination of an ATR inhibitor (VE-822) with oxaliplatin (Vox combination) had a synergistic antitumoral effect and might enable better tumor control in patients with oxaliplatin-resistant CRC." (PMID 40139833, 2025).
tumor (continued). "The index patient in family A06 (A06‐01) carried variants in several classical tumor suppressor genes, including two different variants in MLH1 (A441T and the K618A), a variant in PALB2 (L939W) and several variants in ATM and ATR, all classified as VUS or benign." (PMID 40072281, 2025). "Additionally, an ongoing clinical study is evaluating the efficacy and safety of ART0380 as a monotherapy in patients with tumours exhibiting biological characteristics predictive of sensitivity to ATR inhibition." (PMID 40256842, 2025). "It is also generally believed that tumor cells may adapt to oncogene-induced RS by modulating the intensity of the ATR–Claspin–Chk1 response, as ATR and Chk1 haploinsufficiencies enhance oncogene-induced tumor development." (PMID 41009395, 2025). "Our findings show that RECQL4 expression has divergent patterns across tumor types and that targeting RECQL4 may dampen tumor survival and enhance susceptibility to ATR inhibitor therapy in CNS tumors." (PMID 41317405, 2025). "A second extension could include synthetic lethal interactions with PARP and ATR inhibitors beyond BRCA loss and HRD, such as ARID1A and ATM mutations, which would further help identify tumours most likely to respond to specific treatments." (PMID 39875558, 2025). "The selective inhibition of ATR is a significant attribute of its therapeutic potential in oncology, where ATR inhibitors enhance the efficacy of DNA-damaging agents by exploiting tumour cells’ heightened replication stress and compromised DNA repair mechanisms." (PMID 40256842, 2025). "In contrast, ATR knockout or inhibition results in significant tumour growth suppression." (PMID 40256842, 2025). "Additionally, ATR also functions as a crucial safeguard in maintaining telomere integrity in tumours that alter the alternative lengthening of the telomeres (ALT) pathway." (PMID 40256842, 2025). "Additionally, due to their elevated replication stress, tumour cells exhibit enhanced dependence on the ATR signalling pathway." (PMID 40859871, 2025). "In a xenograft (PDX) model of triple-negative breast cancer (TNBC), the combination of irinotecan (TOP1 inhibitor) and ATR inhibitor VE-822 significantly improved tumor growth inhibition and inhibited CHK1 phosphorylation in SLFN11-negative tumors, overcoming the limitations of single-drug therapy." (PMID 40766331, 2025). "Additionally, pharmacological blockade of ATM/Chk2 and ATR/Chk1 axes enhances the effects of immunotherapy by increasing tumor immunogenicity, promoting T-cell infiltration and activating immune responses." (PMID 40422251, 2025). "In preclinical models, ATM and ATR inhibitors together with IR created a more favorable anti-tumor immune microenvironment (e.g. increased cytotoxic T-cells, decreased Tregs), increased T-cell receptor diversity, generated immunologic memory and combined with immunotherapies improved tumor control." (PMID 40181161, 2025). "Therefore, we decided to thoroughly investigate the relative impact of ATR inhibition, oxaliplatin and Vox on the tumor immune signature." (PMID 40139833, 2025). "Similarly, ATR inhibition augments the radiation-induced inflammatory tumor microenvironment and increases chemokine/cytokine programs consistent with enhanced immune activation." (PMID 41373427, 2025). "This dual profile may also inform treatment, as ARID1A-deficient tumours respond to DNA-damaging agents and immune checkpoint inhibitors, while ATM loss may sensitize tumours to PARP or ATR inhibitors." (PMID 41146957, 2025).
tumor (continued). "Emerging evidence highlights resistance-associated alterations in CCNE1, CDK2, MYC, FOXM1, ECT2, CDC25A/B, and CDK8/CCNC, all of which may reduce tumor dependency on ATR signaling." (PMID 41387887, 2025). "Thus, the combination of ATR inhibition and radiotherapy, specifically proton radiotherapy, is an attractive one for tumor-specific radiosensitization." (PMID 39235982, 2024). "ATR inhibitors are the subject of intense interest due to their potentiation of DNA damage in combination with conventional cytotoxic agents and radiation in a range of tumor sites." (PMID 37936324, 2024). "We hypothesized that combined ATR inhibitors would enhance ablative radiotherapy-induced tumor cell death and potentiate the tumor microenvironment, and the addition of ICI therapy would strengthen systemic antitumor immunity." (PMID 39487895, 2024). "For the first time, an association between components of the KRAS/ATR/CHEK1-signaling pathway, responsible for coordinating replicative stress, and markers of tumor progression, including invasiveness and tumor recurrence, has been established in patients with stage I ECE." (PMID 38669256, 2024). "Moreover, the triple therapy comprising ablative radiotherapy, ATR inhibition, and immune checkpoint inhibitor therapy further reduced the metastatic tumor burden (P < 0.01), indicating enhanced antitumor immunity and a potential abscopal effect." (PMID 39487895, 2024). "High FBXL12 expression is associated with poor survival in patients with high CCNE1 expression, indicating that FBX12-dependent RST initiated by ATR-Chk1 axis activation may contribute to cyclin E-driven tumor malignancy." (PMID 39456601, 2024). "We employed a subcutaneous A549 xenograft flank tumor mouse model to determine whether ATR inhibition enhanced tumor cell killing by ablative radiotherapy and overall survival." (PMID 39487895, 2024). "In turn, the addition of PARP inhibitors to ARID1A-loss tumor cells and the addition of PARP inhibitors to the treatment of ARID1A-loss tumor cells could improve the responsiveness of cells to ATR inhibitors." (PMID 38347608, 2024). "Considering CCNE1 amplification causes replication stress that activates the DNA replication fork stabilizer and regulator of G2/M checkpoint kinase ATR, we sought to further improve anti-tumor efficacy by combining PKMYT1 inhibition (RP-6306) with ATR inhibition (RP-3500)." (PMID 38410486, 2024). "Finally, in that study, the dual inhibition of WEE1 and ATR induced PD-L1 expression on tumour cells, and blocking PD-L1 enhanced the effects of chemotherapies." (PMID 39271762, 2024). "However, the mechanism of the effects of ATR inhibition on the tumor immune microenvironment (TIME) and on immune cells themselves remained largely unclear." (PMID 38402224, 2024). "Also using PARPi synergy with the ICIs in tumours with homologous recombination damage reported increases in the mutational load in tumour cells and increased expression of PD-L1 by ATM-ATR-Checkpoint kinase 1 pathway." (PMID 36845691, 2023). "ATR, on the other hand, is more critical in many tumor cells than it is in normal ones." (PMID 37511442, 2023). "Likewise, ATR inhibition by VE-821 enhanced the response to a single dose irradiation of 6 Gy in a PSN-1 tumor xenograft model in vivo." (PMID 36313934, 2023). "However, the antitumor effect exerted by the combination of ATR inhibitor with topoisomerase (TOP1) inhibitor and the subsequent mechanisms underlying enhanced tumor immunogenicity in SCLC remain poorly understood." (PMID 35957613, 2023).
tumor (continued). "ATR inhibition further increased CAN-2409’s tumor cell killing abilities." (PMID 37228396, 2023). "Furthermore, during development and in the metastatic spread of circulating tumor cells, ATR-defective cells have a defect in neuronal migration." (PMID 37511442, 2023). "Also, an enhanced tumor-inhibitory effect of ATR inhibition in combination with fractionated RT was shown in an immunocompetent mouse model for human papillomavirus (HPV)-positive malignancies." (PMID 37420037, 2023). "Combining an ATR inhibitor with an immune checkpoint blocker is justified since, in addition to increasing DNA damage, the former also decreases PD-L1 levels and boosts anti-tumor immune responses." (PMID 36831197, 2023). "Notably, activation of ATR pathway significantly promotes tumor cell survival, while having minimal impact on normal cells." (PMID 37349788, 2023). "Ataxia telangiectasia and Rad3-related protein (ATR), a kinase in the DNA damage repair pathway, may be important in controlling immunosuppression in the tumor microenvironment." (PMID 37554167, 2023). "For example, we show that GAs in genes such as ARID1A, SMARCA4 and ATR are associated with TMB-high status in a tumour type-specific manner and may thus represent additional biomarkers for immunotherapy in these tumour types." (PMID 37821580, 2023). "In recent years, its pharmacological research has shown that ATR has a variety of pharmacological effects, including anti-epileptic, sedative, hypnotic, anti-convulsant, anti-tussive, anti-asthmatic, anti-oxidant, anti-tumor and so on." (PMID 37007031, 2023). "In our case, array-CGH of constitutive versus tumoral DNA of PED2361.1 (MBC: p.Leu1808*) did not reveal a loss of heterozygosity (LOH) at ATR locus in the tumor." (PMID 36749285, 2023). "Therefore, many clinical trials have investigated HR repair as a potential target for tumor therapy, including ATR, ATM, and Rad51." (PMID 37684630, 2023). "In ATM-deficient cancer cells, the ATR inhibitor ceralasertib combined with the DNA crosslinker, PBD SG-3199, activated dendritic cells in a STING-IFN-dependent manner, externally fortifying tumor immunogenicity." (PMID 37109350, 2023). "This DDR molecular pathway, via its key ATM and ATR proteins, could promote tumor angiogenesis under hypoxic conditions." (PMID 37371032, 2023). "Nevertheless, under hypoxic conditions, this DDR molecular pathway, via its key ATM and ATR proteins, could promote tumor angiogenesis." (PMID 37371032, 2023). "Moreover, ATR inhibition can increase type I interferon (IFN) signaling via induction of cytosolic DNA or RNA in irradiated tumor cells." (PMID 37346039, 2023). "Importantly, tumor-specific alterations such as ATM loss and Cyclin E1 (CCNE1) amplification are more sensitive to ATR inhibition and are being exploited in synthetic lethality (SL) strategy." (PMID 35458687, 2022). "In addition to its primary function associated with SSBs, ATR is also involved in alternative lengthening of telomeres (ALT), a mechanism carried out by the HR machinery, in which cells of many tumor types restore the telomeres achieve immortality." (PMID 35158967, 2022). "Importantly, precise regulation of the final separation of cells at abscission is required for safeguarding genome integrity, likely contributing to ATR’s tumor suppressive functions." (PMID 35754741, 2022). "We then assumed that USP2-AS1 might promote DCAF13 by targeting these putative tumor-suppressive substrates, especially ATR." (PMID 36359803, 2022). "Depletion of MCM6 abolished GC tumor growth and sensitized GC to standard cytotoxic treatments via suppression of the DNA damage-induced ataxia telangiectasia and rad3-related protein/checkpoint kinase 1 (ATR/Chk1) signaling." (PMID 36185598, 2022).
tumor (continued). "Finally, to extend these data into an in vivo setting, we evaluated the anti‐tumor efficacy of the ATR inhibitor in the mPTCL model." (PMID 35510955, 2022). "Oral administration of the ATR inhibitor, AZD6738, decreased growth transiently in ATRX-deficient U251 xenografts, while the combination of temozolomide plus AZD6738 had a more pronounced and persistent inhibitory effect on tumor cell growth." (PMID 35740680, 2022). "As a checkpoint for replication stress and DNA damage in S-phase, ATR is a potential target for sensitizing tumor cells to DNA damage, but the cells’ response to ATR inhibition may depend on the functionality of the DDR machinery." (PMID 35158967, 2022). "In other preclinical tumor models involving ATRi in combination with other DNA-damaging agents, best results are obtained when the DNA-damaging stimulus is given 18 hours prior to addition of an ATR inhibitor." (PMID 36413415, 2022). "It is still unclear whether pharmacological inhibition of DNA-PKcs kinase activity may dampen anti-tumour immunity in contrast to inhibition of other DDR kinases described such as ATM or ATR." (PMID 36106115, 2022). "Indeed, targeted agents against specific components of DNA repair, such as PARP inhibitors, are employed in various tumor types, while others, such as ATR, CHK1 or WEE1 inhibitors, are in clinical development." (PMID 35205700, 2022). "While PTEN-deficient tumor cells were not dependent on DNA-PK for IR resistance nor activated ATR during IR, they showed a significant dependence for the DNA damage kinase ATM." (PMID 35477555, 2022). "Similarly, chemotherapy agents trigger a replication stress response as a result of DNA damage; inhibition of ATR will prevent suppression of this response and in tumor cells that overexpress oncogenes, this can be synthetically lethal." (PMID 36420962, 2022). "Besides ATR mutations, common mutated genes (BRCA1, EGFR, and ROS1) that characterize LUAD were also found in 5 tumor samples." (PMID 35712480, 2022). "Furthermore, inhibition of ATR-related signaling pathways can increase cell apoptosis and effectively improve tumor radiosensitivity." (PMID 35875060, 2022). "Furthermore, MCM6 deficiency sensitized GC cells to chemo- or radiotherapy by causing DNA breaks and blocking ATR/Chk1-mediated DNA damage response (DDR), leading to exacerbated cell death and tumor regression." (PMID 36185598, 2022). "Similar to CHK1 inhibition, recent studies showed that the pharmacological inhibition of ATR may induce cGAS-STING-mediated anti-tumor immunity and may trigger tumors for immune checkpoint blockade." (PMID 35563772, 2022). "Experiments carried out on NPC cells showed that this lncRNA might be a radiosensitizing tumor suppressor reducing these types of molecular pathways through the ATM/ATR-Chk1/Chk2 signaling axis." (PMID 36294743, 2022). "However, the simultaneous regulation of cell cycle check-points and DDR allows cells to maintain a complex balancing act between genomic instability and tumor maintenance, which depends upon the ATR-Chk1 signaling axis." (PMID 35747808, 2022). "Interestingly, the CRC042 model, in which the tumor specific growth rate was significantly decreased with the addition of AZD0156 to irinotecan, does harbor an ATR mutation." (PMID 36309653, 2022). "Since ATRX loss of function and MYCN amplification are reported to be mutually exclusive, and 11q deletion is very rarely observed in MYCN-amplified tumours, we propose PARP and ATR inhibitors may be beneficial to a large subset of high-risk NB patients." (PMID 34944835, 2021). "Moreover, for patients with low replication stress tumors, addition of CDC7 inhibitor will possibly result in increased replication stress and thereby sensitize tumor cells to ATR or CHK1 inhibitors." (PMID 34663432, 2021). "Finally, we observed enhanced synergistic tumor cell killing in ATRX KO cells with combined ATR and PARP inhibition, which is commonly seen in HR-defective cells." (PMID 34118569, 2021).